CACNB3 (calcium voltage-gated channel auxiliary subunit beta 3)
Description:
Regulatory subunit of the voltage-gated calcium channel that gives rise to L-type calcium currents. Increases CACNA1B peak calcium current and shifts the voltage dependencies of channel activation and inactivation (By similarity). Increases CACNA1C peak calcium current and shifts the voltage dependencies of channel activation and inactivation (By similarity).
Synonyms: CAB3; CACNLB3
Tractability: Small molecule: an approved drug acts on it; a structure with a bound ligand is known; a high-quality ligand is known; it belongs to a druggable protein family. PROTAC: its protein half-life has been measured.
Target class: Calcium channel auxiliary subunit beta family; Auxiliary transport protein
Gene: Protein-coding gene on chromosome 12 (48,813,794 to 48,828,941, forward strand). Ensembl gene ENSG00000167535.
Subcellular location: Cytoplasm
Subcellular location (Human Protein Atlas): Golgi apparatus; Vesicles
Pathways (Reactome):
Metabolism: Adrenaline,noradrenaline inhibits insulin secretion; Regulation of insulin secretion
Cellular responses to stimuli: Mechanical load activates signaling by PIEZO1 and integrins in osteocytes
Developmental Biology: NCAM1 interactions
Neuronal System: Presynaptic depolarization and calcium channel opening
Gene Ontology:
Molecular function: protein binding; voltage-gated calcium channel activity; calcium channel regulator activity; high voltage-gated calcium channel activity
Biological process: calcium ion transmembrane transport; calcium ion transport; calcium ion transmembrane transport via high voltage-gated calcium channel; calcium ion transport into cytosol; chemical synaptic transmission; positive regulation of high voltage-gated calcium channel activity; positive regulation of muscle contraction; protein localization to plasma membrane; regulation of membrane repolarization during action potential
Cellular component: cytoplasm; L-type voltage-gated calcium channel complex; membrane; voltage-gated calcium channel complex; cytosol; T-tubule; synapse
Genetic constraint (gnomAD): Loss-of-function variants: 36 observed, 65.84 expected, observed/expected ratio (o/e) 0.55, 90% interval 0.42 to 0.72. The upper end of that interval is the gene's LOEUF score, 0.72, which puts it in group 2 of 6, group 1 being the genes least tolerant of losing a copy. Missense variants: 493 observed, 672.66 expected, observed/expected ratio (o/e) 0.73, 90% interval 0.68 to 0.79. Synonymous variants: 241 observed, 262.76 expected, observed/expected ratio (o/e) 0.92, 90% interval 0.82 to 1.02.
Homologues: Orthologues: dog CACNB3 (99% identical), pig CACNB3 (99% identical), guinea pig CACNB3 (99% identical), mouse Cacnb3 (99% identical), chimpanzee CACNB3 (98% identical), rat Cacnb3 (97% identical), macaque CACNB3 (97% identical), rabbit CACNB3 (96% identical), tropical clawed frog cacnb3 (85% identical), zebrafish cacnb3a (62% identical), zebrafish cacnb3b (61% identical), Drosophila melanogaster Ca-beta (55% identical), and 2 more. Paralogues in human: CACNB4 (67% identical), CACNB2 (62% identical), CACNB1 (59% identical).
Diseases named in the same sentence as CACNB3 in open-access papers:
CACNB3 is named in the same sentence as 15 diseases in open-access papers, as found by Europe PMC text mining. Sharing a sentence is not in itself a finding about the gene and the disease. The quoted sentences say what the papers report.
bipolar disorder (4 papers, 2016 to 2024). A disorder of the brain that causes unusual shifts in mood, energy, activity levels and the ability to carry out day-to-day tasks. "Another example is CACNB3 and CACNG4, calcium channel genes that have been associated with bipolar disorder and major depression(." (PMID 38464225, 2024). "In bipolar disorder, the elevation of miR-34a expression in human neuronal progenitors affected CACNB3 mRNA and protein expression, and resulted in defects in neuronal differentiation." (PMID 36078146, 2022).
abscess (1 paper, 2023). An inflammatory process characterized by the accumulation of pus within a newly formed tissue cavity which is the result of a bacterial, fungal, or parasitic infection or the presence of a foreign body. "Immune cell clusters adjacent to necrotic hepatocytes within abscess were highly heterogenous, consisting of dendritic cells, particularly Cacnb3+ migratory dendritic cells, and other Itgam+ (CD11b) cells, innate lymphoid cells, T cells, neutrophils, monocytes, and macrophages." (PMID 38096412, 2023).
breast carcinoma (1 paper, 2024). "Three ion channel genes KCNK1, CLCN3, and CACNB3, which were overexpressed in breast cancer, and another ion channel gene ANO6, which was underexpressed in breast cancer, were identified by significance analysis of microarrays (SAM)." (PMID 38905316, 2024). "In contrast, the expression of CLCN3, CACNB3, and ANO6 in breast cancer did not correlate significantly with patient prognosis." (PMID 38905316, 2024).
Cerebral ischemia (1 paper, 2022). Restriction of arterial blood supply to the brain associated with insufficient oxygenation to support the metabolic requirements of the tissue. "In a rat model of cerebral ischemia, CACNB3, which might represent functional modules within the ischemic neuronal transcriptome, was induced." (PMID 36078146, 2022).
cervical cancer (1 paper, 2022). A primary or metastatic malignant neoplasm involving the cervix. "After multivariate Cox regression analysis, eight genes were identified as key predictors of HLA-G-driven DEGs in the prognostic risk model for predicting the overall survival of patients with cervical cancer, including CD46, LGALS9, PGM1, SPRY4, CACNB3, PLIN2, MSMO1, and DAGLB." (PMID 35924232, 2022).
cognitive decline (1 paper, 2024). "Tbr (Rank: 14) and Cacnb3 (Rank: 24) were present in all three phenotypes and may be the link between LIB-induced cognitive decline driven by metabolic disruption and synaptic pathology." (PMID 38542311, 2024).
epilepsy (1 paper, 2023). A brain disorder characterized by episodes of abnormally increased neuronal discharge resulting in transient episodes of sensory or motor neurological dysfunction, or psychic dysfunction. "VGCC alterations are linked to pathophysiological processes such as epilepsy, and CACNB3 promotes channel trafficking and regulates gating properties." (PMID 37341859, 2023). "qPCR, IHC, and Western blot results on mTLE and non-epilepsy control subject tissues indicated that CACNB3 expression level alterations were likely to be caused by disease." (PMID 37341859, 2023). "Alterations in VGCC expression levels and functionality are associated with several pathophysiological processes, such as epilepsy, but this is the first time changes in CACNB3 expression have been associated with drug-resistant epilepsy in humans." (PMID 37341859, 2023). "This is the first time changes in CACNB3 expression have been associated with drug-resistant epilepsy in humans, and since efficient therapeutic strategies for the treatment of drug-resistant mTLE are lacking, our finding might represent a step toward designing such new treatment strategies." (PMID 37341859, 2023). "However, temporal lobe neocortical CACNB3 expression levels were also increased in non-epilepsy control subjects, questioning whether the mTLE CACNB3 increased expression levels were caused by brain region differences." (PMID 37341859, 2023). "Among lead targets, we show consistent significant disease-related differences in expression level of CACNB3 in all lead target validation analyses performed, despite using different groups of non-epilepsy control tissues." (PMID 37341859, 2023). "IHC CACNB3 expression level results from temporal lobe neocortex were increased in all layers in mTLE compared to non-epilepsy control subjects, particularly in the upper neocortical layers." (PMID 37341859, 2023). "CACNB3 has not previously been associated with drug resistance in epilepsy, but CACNB3 expression level alterations were reported in studies addressing mental health conditions." (PMID 37341859, 2023). "Hence, we conducted Western blot on hippocampal and temporal lobe neocortical tissues, respectively, from mTLE and non-epilepsy control subjects, to possibly confirm the IHC CACNB3 finding." (PMID 37341859, 2023). "The Western blot result confirmed a significant decrease in CACNB3 expression level in mTLE hippocampus compared to temporal lobe neocortex (Table SI2) using a non-epilepsy cohort with an increased number of control subjects in the group compared to IHC analysis." (PMID 37341859, 2023). "Western blot results also showed a tendency for higher temporal lobe neocortex CACNB3 expression in the mTLE group compared to non-epilepsy controls, although not statistically significant (p-value: 0.083)." (PMID 37341859, 2023). "Western blot protein level results confirmed CACNB3 downregulation in hippocampus compared to temporal lobe neocortex for the mTLE group, but not in the non-epilepsy control subjects, as will be discussed here." (PMID 37341859, 2023).
infantile idiopathic nystagmus (1 paper, 2026). "Here, we report a novel genotype-phenotype correlation that associates sequence alterations in the calcium voltage-gated channel auxiliary subunit beta 3 (CACNB3) gene, encoding the CaVβ3 protein, with idiopathic infantile nystagmus (IIN)." (PMID 41822111, 2026).
cancer (2 papers, 2014 to 2023). A tumor composed of atypical neoplastic, often pleomorphic cells that invade other tissues. "CACNB3 encodes a calcium voltage-gated channel and has no known role in cancer." (PMID 37756103, 2023).
CACNB3 also shares sentences with these, for which no sentence is quoted: depression (2 papers); absence seizures (1); Arthritis (1); dilated cardiomyopathy (1); infection (1); Intellectual disability (1).